TNF (tumor necrosis factor)
Diseases named in the same sentence as TNF in open-access papers (continued):
Sharing a sentence is not in itself a finding about the gene and the disease.
endometritis (continued). "In this study, LPS-induced BEND cell inflammation was used to establish a model of endometritis effects of LPS on expression levels of inflammatory factors in BEND cells IL-1β, IL-6, IL-8, TNF-α for further analysis." (PMID 39682333, 2024). "When compared to resistant cows, endometritis-affected cows had considerably higher levels of the genes TLR4, TLR7, TNF, NCF4, and LITAF expression." (PMID 37756095, 2023). "The expression levels of the genes TLR4, TLR7, TNF-α, NCF4, LITAF, OXSR1, TKT, RPIA, and AMPD1 were significantly greater in endometritis-affected Holstein dairy cows than in resistant ones." (PMID 37368756, 2023). "Using PCR-DNA sequencing for the immunological (TLR4, IL10, TLR7, NCF4, TNF-α, and LITAF) genes, there were changes in the nucleotide sequence between endometritis-affected cows and healthy ones." (PMID 37756095, 2023). "And the signaling transduction of PGD2 through the DP1 receptor in bacteria-mediated endometritis in dairy cows was found to suppress activation of NF-κB and P38 MAPK signaling, thus reducing expression of IL-6, IL-1β, and TNF-α." (PMID 37891648, 2023). "Gene expression levels were considerably higher in endometritis-affected cows than in resistant ones for the genes TLR4, TLR7, TNF-α, NCF4, LITAF, OXSR1, TKT, RPIA, and AMPD1." (PMID 37368756, 2023). "First, we demonstrated that PGD2 inhibited the secretion of the inflammatory cytokines IL-1β, IL-6, and TNF-α to some extent, contributing to inhibition of the phosphorylation of p38, ERK, and NF-κB in bovine endometritis." (PMID 36435808, 2022). "We also found that IAld, indole, and IPA treatment alleviated E. coli-induced endometritis, which was shown by improved uterine inflammatory injury and reduced inflammatory markers including MPO activity, TNF-α, and IL-1β compared with the E. coli group." (PMID 35727038, 2022). "Notably, the LPS-induced tissue levels of IL-1β, IL6, and TNF-α significantly decreased with Cl-amidine treatment, indicating that inhibition of NETs formation in the process of endometritis could be advantageous in protecting uterine tissue from damage and ultimately altered endometritis." (PMID 35565576, 2022). "Previous studies show that mRNA of proinflammatory cytokines interleukin-1 alpha (IL1A), IL1B, IL6, and TNF and expression of chemokines IL8 and CXCL5 increased in endometrial epithelial cells during the estrous cycle and subclinical or clinical endometritis." (PMID 33324700, 2020). "The serum levels of TNF-α and IL-6 (p < 0.01) as well as Hp and SAA (p < 0.001) were higher in cows with subclinical endometritis, while the levels of IL-10 were lower (p < 0.001) compared to the uterine washings." (PMID 25846950, 2015). "The results show that the levels of TNF-α (p < 0.01), IL-6, IL-10 as well as SAA and Hp were significantly higher in the serum of cows with subclinical endometritis compared to the controls (p < 0.001)." (PMID 25846950, 2015). "The aim of the study was to evaluate the concentrations of proinflammatory cytokines: TNF-α and IL-6, anti-inflammatory cytokine IL-10, and APPs - Hp and SAA, in the serum and uterine washings of cows with subclinical endometritis and healthy animals." (PMID 25846950, 2015). "Our results are almost in line with those of50who discovered that in Egyptian buffalo cows with clinical endometritis, the mRNA levels of CAT and GPX had a positive correlation with the blood level of TNF-α (r = 1, P = 0.008 and r = 0.999, P = 0.034), respectively." (PMID 40542007, 2025). "The RT-qPCR analysis of the inflammatory cytokines (IL-1β, IL-6, TNF-α) in the two groups demonstrated that the mRNA expression levels of IL-1β, IL-6, and TNF-α were significantly upregulated in the endometritis group compared to the healthy group (* p < 0.05; ** p < 0.01)." (PMID 40646747, 2025).
endometritis (continued). "Nucleotide sequence variations between healthy and endometritis-affected cows were revealed using PCR-DNA sequencing for immune (TLR4, TLR7, TNF-α, IL10, NCF4, and LITAF), antioxidant (ATOX1, GST, and OXSR1), and erythritol-related (TKT, RPIA, and AMPD1) genes were reported by44." (PMID 38459095, 2024). "Furthermore, leonurine effectively reduces levels of inflammatory cytokines, such as tumor necrosis factor-alpha (TNF-α), interleukin (IL)-6, and IL-1β (p < 0.01), which play a crucial role in regulating acute endometritis." (PMID 39062636, 2024). "Moreover, a study revealed that interferon-tau (IFN-τ) prevents S. aureus-induced endometritis by downregulating the expressions of NF-κB, matrix metalloproteinase 9 (MMP 9), TLR2, TNF-α, IL-1β, and IL-6 levels." (PMID 39408650, 2024). "Molecular genetic analyses of the immunological (TLR4, TLR7, TNF-α, IL10, NCF4, and LITAF), antioxidant (ATOX1, GST, and OXSR1), and erythritol-related (TKT, RPIA, and AMPD1) genes comparing healthy and endometritis cows found differences in nucleotide sequence and transcript levels." (PMID 37368756, 2023). "Single nucleotide variants (SNPs) in the genes were discovered using PCR-DNA sequencing for immune (TLR4, TLR7, TNF-α, IL10, NCF4, and LITAF), antioxidant (ATOX1, GST, and OXSR1), and erythritol-related (TKT, RPIA, and AMPD1) genes found in resistant and endometritis-infected Holstein dairy cows." (PMID 37368756, 2023). "The immune (TLR4, TLR7, TNF-α, IL10, NCF4, and LITAF), antioxidant (ATOX1, GST, and OXSR1), and erythritol-related (TKT, RPIA, and AMPD1) genes in endometritis-affected and healthy Holstein dairy cows were characterized in this research using a PCR-DNA sequencing technique." (PMID 37368756, 2023). "Nucleotide sequence variations between healthy and endometritis-affected cows were revealed using PCR-DNA sequencing for immune (TLR4, TLR7, TNF-α, IL10, NCF4, and LITAF), antioxidant (ATOX1, GST, and OXSR1), and erythritol-related (TKT, RPIA, and AMPD1) genes." (PMID 37368756, 2023). "In the endometrium of repeat breeding cows with and without subclinical endometritis, there were significantly more transcript levels of tumor necrosis factor and inducible nitric oxide synthase." (PMID 37368756, 2023). "Pretreatment with heat-killed C. butyricum did not alter TNF-α and IL-1β levels in E. coli-induced endometritis." (PMID 36321897, 2022). "In mares with endometritis, the concentrations of IL-6 and TNF-α in supernatants from endometrial tissue cultures were increased, compared with mares that did not suffer from endometritis, however, only in the cases of SSE and not ChE." (PMID 27152525, 2016). "The data shows that the levels of TNF-α (p < 0.01), IL-6, IL-10 (68.73 ± 12.15 pg/ml), as well as acute phase proteins (SAA and Hp) in the serum of cows with subclinical endometritis were significantly higher compared to healthy cows (IL-10 53.59 ± 3.19 pg/ml) (p < 0.001)." (PMID 25846950, 2015). "Hence, the high serum levels of TNF-α, interleukins, and CRP could introduce a logical alternative to diagnose clinical endometritis." (PMID 36930327, 2023). "The expression of inflammatory cytokines like the tumor necrosis factor-α (TNF-α), Toll-like receptor (TLR) 4, interleukins (IL), insulin-like growth factor-1 (IGF-1), and IGF-binding protein-2 (IGF-BP-2) were reported to be differentially expressed in the uterine of cows affected with endometritis." (PMID 33477832, 2021). "Changes in TNFα/TNFR1 and 2 expression were discernable in the uteri of cats receiving octane medroxyprogesterone compared with those of estrus and diestrus queens, so this medication may favor the development of endometritis and pyometra in cats." (PMID 25028529, 2014).
Peri-Implantitis (77 papers, 2014 to 2026). An inflammatory process with loss of supporting bone in the tissues surrounding functioning DENTAL IMPLANTS. "The results indicated that smoking and the presence of the TNFα-308 GA/AA genotype significantly increased the risk of peri-implantitis, while the CD14-159 CT/TT polymorphism acted as a protective factor." (PMID 41373620, 2025). "IL-1β +3954 C/T, ET-1 and IL-1β, MMP-8 rs11225395 (T allele), MMP8 (−799 C/T), and CD14 rs2569190 showed consistent associations with increased peri-implantitis risk, while the results for TNF-α −308 G/A were inconsistent across populations." (PMID 41373620, 2025). "TNF-α is a key proinflammatory cytokine implicated in peri-implantitis, known for its role in activating innate immune cells such as macrophages and neutrophils." (PMID 39510521, 2025). "Further research has indicated that pro-inflammatory mediators associated with peri-implantitis include interleukin-1 beta (IL-1β), IL-6, IL-17, and tumor necrosis factor-alpha (TNF-α)." (PMID 39555067, 2024). "Regarding dental implants, a systematic review has reported that the central cytokines associated with peri-implantitis were IL-1β, IL-6, IL-17, TNF-α, RANK, and RANKL." (PMID 38614881, 2024). "Another study demonstrated that the risk of developing peri-implantitis increases with smoking and the presence of the TNFα-308 GA/AA genotype." (PMID 39061710, 2024). "As inflammatory biomarkers, the variations of IL-1β, IL-6, and TNF-α are the most commonly studied functional polymorphisms for peri-implantitis and peri-implant bone loss." (PMID 36643585, 2023). "The GA, AA and A/G genotypes of the TNFα (+308) polymorphism are more frequently found in peri-implantitis and are associated with an increased risk of implant failure." (PMID 37232785, 2023). "The close association of the four genetic variants IL-1a, IL-1b, TNF-a and IL-1RN with the risk of peri-implantitis development or implant loss has been demonstrated in a large number of worldwide association studies and was also confirmed in meta-analyses." (PMID 35819566, 2022). "Certain genetic predispositions to peri-implantitis, such as tumor necrosis factor-alpha (TNF-⍺) or interleukin-1 (IL-1) polymorphisms, showed potential links in the onset of peri-implant diseases, although clear genetic patterns are still to be determined." (PMID 36135154, 2022). "Otherwise, a systematic review concluded that the IL-1β, IL-6, IL-17, and TNF-α were the most frequently reported pro-inflammatory mediators associated with peri-implantitis." (PMID 36233685, 2022). "In our study, we found differences in the levels of MIP-1β and TNF-α in saliva that were associated with the presence of herpesvirus in the peri-implantitis group only." (PMID 30158834, 2018). "Nevertheless, consistent associations were observed for certain polymorphisms—particularly CD14 rs2569190, IL-1β +3954 C/T, and TNF-α −308 G/A—across independent populations, supporting a moderate level of confidence in these findings as potential biomarkers for peri-implantitis susceptibility." (PMID 41373620, 2025). "The main TNFα polymorphism in peri-implantitis is TNFα (+308)." (PMID 37232785, 2023). "TNF-α, IL-1, and IL-6 have been identified as the most essential pro-inflammatory cytokine biomarkers and are strongly linked to the onset, development, and clinical consequences of peri-implantitis." (PMID 36015175, 2022). "During peri-implant infection, the microorganisms through involved cytokines (interleukins 1β, 6, and 10 and TNF-α) could contribute to bone loss in peri-implantitis." (PMID 30050922, 2018). "Pro-inflammatory cytokines such as interleukin-1β, interleukin-6, and tumor necrosis factor can impair osteogenic differentiation and promote osteoclast activation, leading to bone resorption in peri-implantitis." (PMID 41535819, 2026).
Peri-Implantitis (continued). "The results of this study provide significant insights into the roles of IL-6, IL-10, and TNF-α in peri-implantitis, addressing their controversial status as biomarkers." (PMID 40959363, 2025). "The PI, probing depth, and IL-6, IL-10, and TNF-α levels were significantly higher in the peri-implantitis group, with large effect sizes indicating substantial biological differences between the groups." (PMID 40959363, 2025). "This prospective cross-sectional study demonstrated that IL-6, IL-10, and TNF-α levels in PICF were significantly elevated in periodontally healthy patients with peri-implantitis compared to those with healthy-periodontal implants." (PMID 40959363, 2025). "In peri-implantitis, IL-6, IL-1β, TNF-α, MMP-8, and their genetic variations appear to be the most important cytokines not only in pathogenesis but also in their potential diagnostic capabilities." (PMID 41172495, 2025). "Cytokine levels in PICF were markedly elevated in peri-implantitis cases: IL-6 (235.56 ± 56.34 pg/mL vs. 22.88 ± 8.06 pg/mL), IL-10 (73.13 ± 15.11 pg/mL vs. 13.13 ± 4.25 pg/mL), and TNF-α (148.94 ± 53.99 pg/mL vs. 8.31 ± 2.89 pg/mL)." (PMID 40959363, 2025). "Pro-inflammatory cytokine antagonists can effectively block the inflammatory response and bone resorption process of peri-implantitis by specifically inhibiting the activity of key inflammatory mediators such as IL-1β and tumor necrosis factor-α." (PMID 40851867, 2025). "The selection of IL-6, IL-10, and TNF-α in this study was driven by their controversial roles in peri-implantitis." (PMID 40959363, 2025). "Proinflammatory cytokines including TNF-α and IL-1β were significantly elevated in peri-implantitis." (PMID 39195095, 2024). "Observe the effects of treatment on clinical parameters indicative of mucositis or peri-implantitis (Δ PD; Δ PI; Δ BoP) and/or immunological parameters (Δ IL-1β; Δ IL-6; Δ IL-8; TNF-α)." (PMID 38686378, 2024). "It was reported that a high TNF-α concentration induced the downregulation of miRNA-27a and suppressed osteogenic differentiation around the implant during middle and late stages of peri-implantitis." (PMID 38610701, 2024). "Proinflammatory cytokines including TNF-α and IL-1β were statistically greater in peri-implantitis compared to peri-implant tissue in health." (PMID 39195095, 2024). "B cells significantly elevated in peri-implantitis lesions, accompanied by significantly increased levels of IL-1β, TNF-α, IL-4, and basic fibroblast growth factor." (PMID 39555067, 2024). "Several studies have reported higher levels of IL-1β and tumor necrosis factor-alpha (TNF-α) in the peri-implant crevicular fluid (PICF) of implants with peri-implantitis than in healthy implants." (PMID 38203822, 2024). "Specific immunity in peri-implantitis is characterized by elevated levels of pro-inflammatory cytokines such as IL-1β, IL-6, IL-17, and TNF-α, secreted by activated T cells and other immune cells." (PMID 39555067, 2024). "In summary, our findings suggest a dynamic interplay in peri-implantitis, where the concomitant rise in TNF-α and VEGF accentuates proinflammatory activity." (PMID 38477721, 2024). "Reducing IL-1β and TNF-α is crucial for enhancing the longevity of dental implants because these cytokines are key mediators in the inflammatory process that can lead to peri-implantitis." (PMID 39590543, 2024). "As with other chronic inflammatory diseases, peri-implantitis progression is due to inflammatory cytokines such as IL-1β, TNF-α, and IL-6." (PMID 36768829, 2023). "In this work only few authors have recognized a relation between the TNF-α (− 308) SNP and peri-implantitis." (PMID 35061134, 2022). "TNF-α plays an important role in the pathogenesis of peri-implantitis and is involved at an early stage in the inflammatory cascade to promote the release of other inflammatory mediators to amplify inflammation." (PMID 36550581, 2022).
Peri-Implantitis (continued). "In this study, pro-inflammatory cytokines of IL-1β, IL-6, IL-17A, and TNF-α were significantly higher in peri-implantitis than those in healthy implants, and this result is consistent with another study." (PMID 36233685, 2022). "This is supported by the findings that significantly higher levels of IL-1β and TNFα in the peri-implant crevicular fluid (PICF) are observed in patients with peri-implantitis than in healthy controls." (PMID 34610045, 2021). "Another research confirmed significantly higher serum level of TNF-α in peri-implantitis patients compared to controls, indicating the pivotal role of these cytokines in peri-implantitis." (PMID 34300145, 2021). "One research showed increased salivary TNF-α level in cases with peri-implant clinical condition, especially in patients with peri-implantitis." (PMID 34300145, 2021). "It has been shown that the levels of TNF-α and IL-1β in PICF were positively correlated associated with peri-implant mucositis and peri-implantitis." (PMID 34429083, 2021). "According to the results, IL-1β, IL-6, and TNF-α, levels were significantly higher in mucositis and peri-implantitis than in healthy implants." (PMID 33291232, 2020). "The salivary concentration of TNF-α was increased in individuals with worse periodontal and peri-implant clinical condition and in those with a higher incidence of peri-implantitis, especially in the GNTP group." (PMID 30810638, 2019). "In the comparison of salivary markers between patients who were positive and those who were negative for herpesvirus (independent of peri-implant condition), we found significantly higher levels of MIP-1β and TNFα in the peri-implantitis group." (PMID 30158834, 2018). "The association of the presence or absence of herpesvirus with the salivary markers was statistically significant for MIP-1β (p = 0.0087) and TNF-α (p = 0.0437) only in the peri-implantitis group." (PMID 30158834, 2018). "When the presence or absence of virus with salivary markers was compared, significant differences for MIP-1β and TNF-α were found only in the peri-implantitis group." (PMID 30158834, 2018). "Similar to IL-1, elevated TNFα levels have been observed in crevicular fluid and saliva of patients with active peri-implantitis lesions and shown to directly correlate with the degree of clinical severity of peri-implant disease." (PMID 30386510, 2018). "This preclinical study therefore advocates that neutralizing antibodies be further tested against IL1β, IL6, or TNFα in clinical settings for managing the aseptic loosening of orthopedic prostheses and oral peri-implantitis." (PMID 30619321, 2018). "Similarly, TNF-α, which is critical for bone remodeling, shows elevated levels in peri-implantitis but lacks a consistent correlation with clinical parameters, such as probing depth, raising questions about its specificity." (PMID 40959363, 2025). "Statistical analysis (t-tests and correlations, p < 0.05) revealed significantly elevated levels of IL-1β, MMP-8 and TNF-α in peri-implantitis patients, with IL-1β and MMP-8 strongly correlating with probing depth and TNF-α moderately correlating with bone loss." (PMID 41907937, 2025). "Thus, we show that salivary IL-1β, MMP-8 and TNF-α show strong potential as reliable, non-invasive biomarkers for early detection and monitoring of peri-implantitis." (PMID 41907937, 2025). "Furthermore, TNF-α levelsare reported to be elevated in peri-implantitis patients relativeto healthy individuals." (PMID 39792796, 2025). "The significant elevations in IL-6, IL-10, and TNF-α levels in the peri-implantitis group compared to those in the healthy implant group, as observed in this study, can be attributed to the heightened inflammatory response characteristic of peri-implantitis." (PMID 40959363, 2025).